BATF2 (basic leucine zipper ATF-like transcription factor 2)
Diseases named in the same sentence as BATF2 in open-access papers (continued):
Sharing a sentence is not in itself a finding about the gene and the disease.
lung carcinoma (3 papers, 2019 to 2023). "To further understand how BATF2 regulates PD-L1, using the TCGA database, we found that lung cancer patients with high BATF2 are negatively correlated with ZEB2 and PI3K signaling pathway." (PMID 37777155, 2023). "Next, we investigated the role of BATF2 in vitro by using human lung cancer cell lines (NCI-H1299, NCI-H1650, and NCI-H1975)." (PMID 37777155, 2023). "In summary, we found that BATF2 is a novel regulator of PD-L1 and that BATF2 inhibits PD-L1 expression in lung cancer as well as promotes tumor immune infiltration." (PMID 37777155, 2023). "To explore the relationships between BATF2 and PD-L1 expression, we initiated an observational, analytical, open retrospective study (ChiCTR2000033546) involving 18 stage IV lung cancer patients who were about to receive immunotherapy." (PMID 37777155, 2023). "Based on bioinformatics analysis, we found that the function of BATF2 in promoting antitumor immune response in patients with non–small cell lung cancer, which is mediated by BATF2, enhances CD8+ T-cell infiltration as well as activation." (PMID 37777155, 2023). "To determine whether BATF2 could modulate PD-L1 in vivo, we first tested the expression of PD-L1 in nude mice with orthotopic lung cancer." (PMID 37777155, 2023). "We confirmed this hypothesis in vitro by using human lung cancer cell lines and found that increasing the expression of BATF2 in lung cancer cells can prevent ZEB2 from entering the nucleus." (PMID 37777155, 2023). "In addition, in patients’ samples, we also found increased p-AKT, p-PI3K, ZEB2, and PD-L1 levels from lung cancer patients with low BATF2 expression." (PMID 37777155, 2023). "Importantly, from our previous work, we found that BATF2 deficiency facilitates EMT transition, which contributes to lung cancer metastasis by regulating β-catenin–glycogen synthase kinase 3β pathway." (PMID 37777155, 2023).
gastric tumor (2 papers, 2021 to 2024).
glioma (2 papers, 2021 to 2025). A benign or malignant brain and spinal cord tumor that arises from glial cells (astrocytes, oligodendrocytes, ependymal cells). "Further, BATF2 also decreased myeloid-derived suppressor cell recruitment, which contributed to reduced glioma growth, suggesting additional roles in modulating pathological microenvironments within the CNS." (PMID 40945729, 2025). "U87-MG glioma cells were then used as a model of BATF2 overexpression for reciprocal analysis of BATF2-regulated cell cycle genes." (PMID 40945729, 2025). "Of note, our novel findings established the regulatory functions of BATF2 and BATF2-EVs in regulating MDSCs and proposed the potential of BATF2+ plEVs as a biomarker to reflect glioma stage." (PMID 33452462, 2021). "Taken together, our study identified novel regulatory functions of BATF2 in regulating MDSCs recruitment, providing a prognostic value in terms of the number of BATF2+ plEVs in glioma stage." (PMID 33452462, 2021). "Here, we show that BATF2 inhibits glioma growth and myeloid-derived suppressor cells (MDSCs) recruitment." (PMID 33452462, 2021). "In particular, BATF2 upregulation inhibited the secretion of SDF-1α during glioma progression upon intracranial tumour cell injection for 7, 14, and 21d." (PMID 33452462, 2021). "Specifically, detection of EVs in 24 pairs of gliomas and healthy donors at different stages revealed that the abundance of BATF2-positive EVs in plasma (BATF2+ plEVs) can distinguish stage III–IV glioma from stage I–II glioma and healthy donors." (PMID 33452462, 2021). "Collectively, BATF2 protein status can provide a GBM-specific liquid biopsy that can help evaluate glioma staging." (PMID 33452462, 2021). "Furthermore, by calculating the numbers of BATF2-positive EVs in plasma, we proposed the clinical use of BATF2+plEVs as a biomarker to reflect glioma stage." (PMID 33452462, 2021). "Furthermore, digital EVs detection in 24 pairs of glioma plasmas at different stages indicated that plasma BATF2+ EVs can constructively distinguish stage III–IV glioma from stage I–II glioma and healthy donors." (PMID 33452462, 2021). "In conclusion, we found that BATF2 inhibits MDSCs infiltration and glioma growth." (PMID 33452462, 2021). "Interestingly, extracellular vesicles (EVs) from BATF2-overexpressing glioma cell lines (BATF2-EVs) inhibited MDSCs chemotaxis in vitro." (PMID 33452462, 2021). "Indeed, our data confirmed that higher expression of BATF2 can be detected in EVs released from BATF2-overexpressing glioma cells." (PMID 33452462, 2021). "To determine whether our findings are clinically relevant, we stained glioma tissue sections (n = 50) for BATF2, SDF-1α, HIF-1α (hypoxia marker), CD14 (Mo-MDSCs marker), and CD33 (MDSCs marker)." (PMID 33452462, 2021). "Hence, we next sought to calculate BATF2+ EV abundance in tumour tissues and plasma in glioma patients and in healthy donors by quantitative Exo-Counter detection." (PMID 33452462, 2021). "Moreover, EVs from BATF2-overexpressing glioma cells inhibited MDSCs recruitment in vitro." (PMID 33452462, 2021). "We also performed ELISA detection and found that BATF2 upregulation significantly decreased VEGFA, MMP2, and MMP-9 levels in glioma tissues (VEGFA: p < 0.001; MMP2: p < 0.01; MMP-9: p < 0.01) and exhibited decreased MMP-9 staining in U251-BATF2 tumour." (PMID 33452462, 2021). "We detected BATF2 expression at both the mRNA and protein levels in a human astrocyte cell line (HA1800) and five distinct glioma cell lines (U251, U87-MG, LN-18, U118-MG, and A172)." (PMID 33452462, 2021). "Herein, we established glioma model using a mouse glioma cell line, GL261, and stable cell lines, GL261-BATF2, and found that overexpression of BATF2 inhibited GL261 subcutaneous tumour growth, as expected." (PMID 33452462, 2021).
glioma (continued). "Interestingly, Cell Counting Kit-8 analyses demonstrated that both overexpression and downregulation of BATF2 in U251, U87-MG, U118-MG, and A172 glioma cells did not affect cell viability in vitro." (PMID 33452462, 2021). "However, the role of BATF2 in glioma growth and the tumour microenvironment is not completely understood." (PMID 33452462, 2021). "Therefore, we hypothesised that BATF2 may not directly regulate glioma cell proliferation, but affects the tumour microenvironment instead." (PMID 33452462, 2021).
influenza (2 papers, 2018 to 2024). An acute viral infection of the respiratory tract, occurring in isolated cases, in epidemics, or in pandemics; it is caused by serologically different strains of viruses (influenzaviruses) designated A, B, and C, has a 3-day incubation period, and usually lasts for 3 to 10 days. "In previous analysis, BATF2 is an important regulator of the innate immune system and has high expression in human lung structural cells infected with influenza, indicating that BATF2 could play a critical role in host antiviral immune, but further studies are needed." (PMID 38229736, 2024).
leukaemia (2 papers, 2016 to 2021). "Our previous study reported a moderate level of BATF2 expression in the K562 leukemia cell line and BATF2 downregulation-induced apoptosis and proliferation inhibition in K562 cells." (PMID 34778372, 2021).
lymph node metastasis (2 papers, 2012 to 2025). "The intersection analysis revealed that three factors, GSDMD, CCND1, and BATF2, were upregulated in postchemotherapy OSCC tumor tissues and highly expressed in tumors from patients with neck lymph node metastasis." (PMID 40178046, 2025).
melanoma (2 papers, 2021 to 2022). A malignant, usually aggressive tumor composed of atypical, neoplastic melanocytes. "Altered tumor cells in the advanced stages of melanoma release Toll-like receptor ligands, such as damage-associated molecular patterns that induce BATF2 expression." (PMID 36143291, 2022).
prostate carcinoma (2 papers, 2021). A carcinoma that arises from epithelial cells of the prostate gland. "Aberrant BATF2 expression in prostate cancer is significantly correlated with serum PSA level, clinical stage, and distant metastasis." (PMID 34778372, 2021).
pulmonary TB (2 papers, 2016 to 2023). "Elevated BATF2 classified cases of pulmonary TB with a ROC AUC of 0.98 and extrapulmonary cases with a ROC AUC of 0.96." (PMID 27734027, 2016).
tongue squamous cell carcinoma (2 papers, 2024). A squamous cell carcinoma that arises from the tongue. "In tongue squamous cell carcinoma (TSCC), METTL14 enhanced VEGFA expression and promoted TSCC development and angiogenesis by inhibiting basic leucine zipper ATF-like transcription factor 2 (BATF2)." (PMID 39033180, 2024). "Similarly, METTL14 induces the expression of basic leucine zipper ATF-like transcription factor 2 (BATF2), which indirectly upregulates VEGFA secretion and promotes angiogenesis in tongue squamous cell carcinoma (TSCC)." (PMID 39098905, 2024).
breast invasive carcinoma (1 paper, 2021). "The pan-cancer analysis showed that the expression level of BATF2 mRNA in breast invasive carcinoma (BRCA) was slightly lower than that in normal controls, but without a significant difference." (PMID 34565331, 2021). "However, the survival analysis of BATF2 expressions in HPA database showed that BATF2 expression (high =254 versus low = 821) yielded a P value of 0.053 in predicting the OS of the breast invasive carcinoma patients." (PMID 34565331, 2021).
COVID-19 (1 paper, 2022). A disease caused by infection with severe acute respiratory syndrome coronavirus 2. "A recent study in COVID-19 host genetics found that BATF2 controls the production of cytokines from CD4+ T-cells and macrophages in mice and participates in interferon signaling, highlighting a potential immunotherapeutic target to mitigate COVID-19." (PMID 35746678, 2022).
epilepsy (1 paper, 2023). A brain disorder characterized by episodes of abnormally increased neuronal discharge resulting in transient episodes of sensory or motor neurological dysfunction, or psychic dysfunction. "Here, we report a homozygous loss-of-function mutation in the immunomodulatory transcription factor gene BATF2 in three siblings of a Turkish family suffering from epilepsy and mental retardation." (PMID 36672163, 2023). "BATF2 is, therefore, a novel disease-associated gene candidate for severe epilepsy and mental retardation related to dysregulation of immune responses, which underscores the relevance of neuroinflammation for epilepsy." (PMID 36672163, 2023). "We demonstrate here that three siblings suffering from epilepsy and mental retardation due to a homozygous loss-of-function mutation in BATF2 show important hallmarks of type I interferonopathy." (PMID 36672163, 2023).
Fever (1 paper, 2016). Body temperature elevated above the normal range. "Despite performing better than BATF2 for discriminating between active TB and Fever cases, these ROC AUCs were significantly lower than those achieved by these signatures in comparing active TB with healthy states." (PMID 27734027, 2016).
fibrosarcoma (1 paper, 2024). A malignant mesenchymal fibroblastic neoplasm affecting the soft tissue and bone. "Besides, BATF2 mRNA and protein expression was also downregulated in human fibrosarcoma cells (HT-1080) and synovial sarcoma cells (SW-982), compared with that in human skin fibroblast cells (HSF)." (PMID 38420020, 2024).
gastrointestinal infection (1 paper, 2019). "Thus, it would be interesting to identify the role of BATF2-dependent suppression of ILC3 responses in gastrointestinal infection in future studies." (PMID 30753547, 2019).
ileitis (1 paper, 2019). "Similar to most CD patients, Batf2−/− mice, in which IL-23 is abnormally produced in the intestinal mucosa, spontaneously developed ileitis, suggesting that BATF2 might be required for the inhibition of IL-23-mediated CD-like intestinal inflammation." (PMID 30753547, 2019).
listeriosis (1 paper, 2019). A bacterial infection caused by Listeria monocytogenes. "Together, our data reveal a regulatory role of Batf2 on the host immune responses to Type 1 (TB and listeriosis) and Type 2 (schistosomiasis) diseases." (PMID 30542107, 2019). "Altogether, our findings showed that Batf2 plays a deleterious key role in the host immunity against listeriosis." (PMID 30542107, 2019). "We further explored whether Batf2 may have a wider importance in Type 1 infectious diseases using experimental murine listeriosis." (PMID 30542107, 2019). "Indeed, Batf2 expression was increased in spleen and liver during listeriosis." (PMID 30542107, 2019).
lymphoma (1 paper, 2024). A malignant (clonal) proliferation of B- lymphocytes or T- lymphocytes which involves the lymph nodes, bone marrow and/or extranodal sites. "Our previous studies have reported glucocorticoid receptor, a transcriptional factor, which suppresses lymphoma cells through inducing BATF2 expression." (PMID 38420020, 2024).
malnutrition (1 paper, 2021). Inadequate nutrition resulting from poor diet, malabsorption, or abnormal nutrient distribution. "The single gene biomarkers NPC2 and BATF2 were very effective in distinguishing between TB and LTBI in malnutrition." (PMID 33482742, 2021).
metastatic cancer (1 paper, 2012). A carcinoma which has spread from the original site of growth to another anatomic site. "The SARI (suppressor of AP-1, regulated by IFN) gene, which is also called BATF2, is associated with the risk of several kinds of cancer, and loss of SARI expression is frequently detected in aggressive and metastatic cancer." (PMID 23049725, 2012).
multiple sclerosis (1 paper, 2025). A progressive autoimmune disorder affecting the central nervous system resulting in demyelination. "Further, we found that BATF2 is expressed in the nucleus of astrocytes in the core of multiple sclerosis lesions, where astrocytes proliferate and participate in glial scar formation." (PMID 40945729, 2025).
non-small cell lung carcinoma (1 paper, 2021). A group of at least three distinct histological types of lung cancer, including non-small cell squamous cell carcinoma, adenocarcinoma, and large cell carcinoma. "Consistently, other studies also suggest that a low BATF2 level is a risk factor for the poor prognosis in non-small cell lung cancer; BATF2 deletion promotes the EMT process, leading to LUAD cell invasion and metastasis." (PMID 34565331, 2021).
ovarian carcinoma (1 paper, 2021). A malignant neoplasm originating from the surface ovarian epithelium. "Although CD38, BATF2, and HLA-DOB have no statistical significance, they show an increasing trend of expression in ovarian cancer." (PMID 34868310, 2021).
psoriasis (1 paper, 2016). An autoimmune condition characterized by red, well-delineated plaques with silvery scales that are usually on the extensor surfaces and scalp. "Of the five genes (BATF2, HRNR, SIGLEC1, SLC4A11, CXCL10) uniquely identified by multiDE (with Bonferroni adjustment), four were found to be closely related to psoriasis." (PMID 27334001, 2016).
sarcoma (1 paper, 2024). A usually aggressive malignant neoplasm of the soft tissue or bone. "In summary, this study identified BATF2 as the target gene of miR-939-3p in sarcoma, and revealed that both upregulated miR-939-3p and downregulated BATF2 expression levels were significantly associated with a poor prognosis of sarcoma patients." (PMID 38420020, 2024). "The downregulation of BATF2 was negatively associated with the prognosis of sarcoma patients." (PMID 38420020, 2024). "In this study, we demonstrated a downregulation of BATF2 in sarcoma, which was positively correlated with prognosis." (PMID 38420020, 2024). "It was found that overexpression of BATF2 significantly alleviated the miR-939-3p-mediated suppression of BATF2 expression and promotion of sarcoma cell proliferation, as well as cell migration and invasion." (PMID 38420020, 2024). "It was found that BATF2 mRNA and protein levels were significantly decreased in 12 cases of sarcoma tissues, compared to the corresponding adjacent tissues." (PMID 38420020, 2024). "Further mechanistic studies demonstrated that miR-939-3p promoted sarcoma cell proliferation via binding to the 3’ UTR of BATF2." (PMID 38420020, 2024). "In this study, we found that BATF2 was downregulated in sarcoma tissues and cells, correlating with a poor prognosis of sarcoma patients." (PMID 38420020, 2024). "In this study, we demonstrated that the expression of BATF2 was downregulated in human sarcoma tissues and cell lines." (PMID 38420020, 2024). "The expression levels of BATF2 and miR-939-3p were evaluated by using human sarcoma samples, cell lines and xenograft mouse models." (PMID 38420020, 2024). "In vitro and in vivo experiments revealed that miR-939-3p enhanced sarcoma proliferation through suppressing BATF2 expression via binding to its 3’ UTR." (PMID 38420020, 2024). "We and others have previously found that BATF2 is an important tumor suppressor in many cancers, although its role in sarcoma remains unknown." (PMID 38420020, 2024). "Further, sarcoma patients were divided into two groups according to BATF2 expression levels." (PMID 38420020, 2024). "Further investigation revealed that BATF2 inhibited the proliferation of sarcoma cells, although the regulatory mechanism and its role in sarcoma remain unclear." (PMID 38420020, 2024). "Since miRNAs play an extensive role in modulating gene expression in sarcoma, we hypothesized that BATF2 might be regulated by miRNA." (PMID 38420020, 2024). "Moreover, miR-939-3p overexpression suppressed sarcoma cell proliferation, which was significantly attenuated by the restoration of BATF2, while siRNA-mediated knockdown of BATF2 aggravated the miR-939-3p-induced promotion of sarcoma cell proliferation." (PMID 38420020, 2024). "Collectively, these findings identified miR-939-3p as a novel regulator of BATF2, as well as a prognostic biomarker in sarcoma, and revealed that suppressing miR-939-3p or inducing BATF2 expression may serve as a promising therapeutic strategy against sarcoma." (PMID 38420020, 2024). "However, the precise molecular mechanism by which miRNAs regulate BATF2 to enhance sarcoma growth remains elusive." (PMID 38420020, 2024). "Nevertheless, these studies have still not clarified the reason for the downregulation of BATF2, especially in sarcomas." (PMID 38420020, 2024). "Accumulated studies suggested basic leucine zipper transcription factor ATF-like 2 (BATF2) as a candidate tumor suppressor, but its specific role and mechanism in sarcoma remain unclear." (PMID 38420020, 2024). "However, neither the mimic nor the inhibitor of miR-455-5p could regulate BATF2 expression, suggesting that BATF2 expression was repressed by miR-939-3p in sarcoma." (PMID 38420020, 2024). "Besides, miR-939-3p could neither further enhance sarcoma cell proliferation nor regulate AP-1 activity or MET expression, when BATF2 was knocked down by a large amount of siRNA in HT-1080 cells." (PMID 38420020, 2024).